NOX5 (NADPH oxidase 5)
Description:
Calcium-dependent NADPH oxidase that catalyzes the generation of superoxide from molecular oxygen utilizing NADPH as an electron donor. Also synthesizes NAADP from its reduced NAADPH form which promotes Ca(2+) signaling during T cell activation. May play a role in cell growth and apoptosis. [Isoform v2]: Calcium-dependent NADPH oxidase that catalyzes the generation of superoxide from molecular oxygen utilizing NADPH as an electron donor. Involved in endothelial generation of reactive oxygen species (ROS), proliferation and angiogenesis and contributes to endothelial response to thrombin. Regulates redox-dependent processes in lymphocytes and spermatozoa. [Isoform v1]: Calcium-dependent NADPH oxidase that catalyzes the generation of superoxide from molecular oxygen utilizing NADPH as an electron donor. [Isoform v5]: This isoform lacks calcium-binding domains and was showed to present a NADPH oxidase activity in a calcium-independent manner. May be involved in endothelial generation of reactive oxygen species (ROS), proliferation and angiogenesis and contribute to endothelial response to thrombin. However another study showed an absence of oxidase activity. Subject to rapid degradation. [Isoform v3]: Lacks calcium-dependent NADPH oxidase activity. [Isoform v4]: Lacks calcium-dependent NADPH oxidase activity.
Synonyms: NOX5A; NOX5B
Tractability: Small molecule: a structure with a bound ligand is known; a high-quality ligand is known; it belongs to a druggable protein family. Antibody: UniProt places it where antibodies can reach, with high confidence; its Gene Ontology location is reachable by antibodies, with high confidence; UniProt predicts a signal peptide or a membrane-spanning region. PROTAC: a small molecule that binds it is known.
Target class: Transmembrane 1-electron transfer carriers; Transporter
Gene: Protein-coding gene on chromosome 15 (69,014,695 to 69,062,762, forward strand). Ensembl gene ENSG00000255346.
Subcellular location: Endoplasmic reticulum (Isoform v2); Cell membrane; Endoplasmic reticulum (Isoform v5)
Pathways (Reactome):
Cellular responses to stimuli: Detoxification of Reactive Oxygen Species
Gene Ontology:
Molecular function: proton channel activity; superoxide-generating NADPH oxidase activity; flavin adenine dinucleotide binding; heme binding; NADP binding; superoxide-generating NAD(P)H oxidase activity; calcium ion binding; oxidoreductase activity
Biological process: endothelial cell proliferation; proton transmembrane transport; superoxide anion generation; apoptotic process; cytoskeleton-dependent cytokinesis; defense response; positive regulation of cytokine production; regulation of fusion of sperm to egg plasma membrane
Cellular component: endoplasmic reticulum; plasma membrane; endoplasmic reticulum membrane; NADPH oxidase complex
Genetic constraint (gnomAD): Loss-of-function variants: 71 observed, 80.94 expected, observed/expected ratio (o/e) 0.88, 90% interval 0.72 to 1.07. The upper end of that interval is the gene's LOEUF score, 1.07, which puts it in group 4 of 6, group 1 being the genes least tolerant of losing a copy. Missense variants: 960 observed, 998.49 expected, observed/expected ratio (o/e) 0.96, 90% interval 0.91 to 1.01. Synonymous variants: 401 observed, 404.19 expected, observed/expected ratio (o/e) 0.99, 90% interval 0.91 to 1.08.
Homologues: Orthologues: chimpanzee NOX5 (96% identical), macaque NOX5 (92% identical), dog NOX5 (84% identical), pig NOX5 (83% identical), rabbit NOX5 (79% identical), tropical clawed frog nox5 (64% identical), zebrafish nox5 (64% identical), Drosophila melanogaster Nox (47% identical). Paralogues in human: DUOX1 (27% identical), DUOX2 (27% identical), NOX1 (23% identical), NOX3 (22% identical), CYBB (22% identical), NOX4 (19% identical).
Diseases named in the same sentence as NOX5 in open-access papers:
NOX5 is named in the same sentence as 101 diseases in open-access papers, as found by Europe PMC text mining. Sharing a sentence is not in itself a finding about the gene and the disease. The quoted sentences say what the papers report.
atherosclerosis (27 papers, 2014 to 2025). A disease characterized by the build-up of fatty material and calcium deposition in the arterial wall resulting in partial or complete occlusion of the arterial lumen. "Overexpression of NOX5 is associated with numerous human diseases, including cardiovascular diseases, nicotine-related atherosclerosis, renal injury, diabetic nephropathy, and cancers, making NOX5 an attractive drug target." (PMID 38734761, 2024). "In search for a causal mechanism in atherosclerosis, the superoxide-forming Nox5 was such a highly promising candidate." (PMID 35798762, 2022). "The upregulation of NOX5 has been associated with several diseases, including atherosclerosis, acute myocardial infarction, aneurysms, and hypertension." (PMID 29348517, 2018). "However, despite its attractiveness and considerable circumstantial clinical evidence, our data argue against a previously unrecognized direct causal or aggravating role of Nox5 in diet-related or ApoE−/− induced atherosclerosis." (PMID 35798762, 2022). "Based on the fact that histone acetylation induces chromatin relaxation and activation of gene expression, we hypothesized that the upregulation of Nox5 in inflammation-associated atherosclerosis may be partially mediated by alterations in chromatin topology." (PMID 31565149, 2019). "Because NOX5 is also involved in a worse outcome in stroke —for which hypertension is a major risk factor —and correlates with atherosclerosis, this approach may lower not only blood pressure but also 2 major consequences of hypertension, stroke and myocardial infarction." (PMID 33170835, 2020). "NOX5 is expressed in all vascular wall cell types and plays a role throughout atherosclerosis progression." (PMID 40076813, 2025). "In human coronary artery plaques, NOX5 shows elevated expression in endothelial cells during early atherosclerosis and in both endothelial cells and VSMCs in advanced coronary artery disease." (PMID 40076813, 2025). "We have recently generated a NOX5-deficient rabbit line, where we observed a protective role of NOX5 against the development of atherosclerosis induced by cholesterol feeding." (PMID 37821487, 2023). "In inflammation-associated atherosclerosis, HAT1 correlates with upregulation of NADPH oxidase 5 (NOX5)." (PMID 37048148, 2023). "A recent study demonstrated a novel role for NOX5 in protecting against the progression of atherosclerosis." (PMID 35740948, 2022). "NOX5 contributes to coronary artery smooth muscle cell contraction, angiogenesis and atherosclerosis progression." (PMID 35740948, 2022). "NOX5 overexpression in endothelial cells leads to phenotypic changes that can lead to endothelial dysfunction, the onset of atherosclerosis, myocardial infarction, and stroke." (PMID 36358519, 2022). "Some studies showed that NOX5 contributes to vascular and kidney pathologies, but a recent study demonstrated a potential protective role of NOX5 against atherosclerosis in rabbits." (PMID 35740948, 2022). "Together with these vascular alterations, NOX5 activity has been related to several CVD such as atherosclerosis, stroke post-reoxygenation damage, and diabetic nephropathy." (PMID 36358519, 2022). "NOX1, NOX2, NOX4, and NOX5 appear to be of particular interest for atherosclerosis, but, unfortunately, data which demonstrate the particular functions and their mechanisms are disparate." (PMID 32664404, 2020). "In terms of human atherosclerosis, Nox5 expression level was found to be increased in atherosclerotic lesions." (PMID 33510639, 2020). "Recently, the Ca2+ regulated NADPH oxidase, NOX5, was found to be overexpressed in RBCs during vascular diseases, as well as in endothelium and vascular smooth muscle cells during atherosclerosis, vascular inflammationn, angiogenesis and in human cancers." (PMID 31838004, 2020). "Human studies demonstrated increased vascular Nox5 expression in atherosclerosis, hypertension, myocardial infarction, and aortic aneurysm." (PMID 30334629, 2019).
atherosclerosis (continued). "We have previously reported that Nox5 expression is significantly upregulated in atherosclerosis and is robustly expressed in the CD68+ Mac-rich area within human carotid artery atherosclerotic plaques." (PMID 31565149, 2019). "Whilst Nox1, Nox2, and Nox4 type oxidases have been extensively investigated in various experimental models, the precise function and the regulatory mechanisms of the newly identified calcium-dependent Nox5 in Mac remain elusive, especially in atherosclerosis." (PMID 31565149, 2019). "Hitherto, the role of histone acetylation-related mechanisms in atherosclerosis and, in particular, in the regulation of Nox5 expression is poorly defined." (PMID 31565149, 2019). "In human atherosclerosis, oxidative and inflammatory processes involve increased expression and activation of NOX5 in vascular cells and resident macrophages." (PMID 30801870, 2019). "The aim of this study was to investigate the expression pattern of key histone acetyltransferase subtypes (p300, HAT1) in human atherosclerosis and to determine their role in mediating the upregulation of Nox5 in macrophages under inflammatory conditions." (PMID 31565149, 2019). "Nox5 expression and activity is increased during hypertension and atherosclerosis, suggesting the importance of Nox5 ROS production for vascular remodeling in hypertension." (PMID 28505091, 2017). "Consistent with previous studies indicating ROS play a role in atherosclerosis and restenosis, our findings demonstrate that knockdown of NOX5 inhibits mitogen-induced CSMC migration." (PMID 25144362, 2014). "The overproduction of ROS from Nox5 is thought to contribute to human disease, such as human coronary artery disease, atherosclerosis, acute myocardial infarction, fetal ventricular septal defect, and cancer." (PMID 24505490, 2014). "Moreover, NOX5 has a protective effect on rabbit arteries, and knocking out NOX5 will aggravate rabbit atherosclerosis." (PMID 36860953, 2023). "Increased ROS production from NOX5 contributes to atherosclerosis." (PMID 35740948, 2022). "Indeed, early expression of the ROS forming NADPH oxidase type 5 (Nox5) in vascular endothelial cells correlates with atherosclerosis and aortic aneurysm." (PMID 35798762, 2022). "Because Nox5 is missing from the mouse genome, a knock-in mouse model expressing human Nox5 in its physiological location of endothelial cells (eNOX5ki/ki) was tested as a possible new humanised mouse atherosclerosis model." (PMID 35798762, 2022). "Moreover, given the role of Nox5 in diabetic complications and because atherosclerosis is accelerated in diabetes, we further induced diabetes in some of the eNOX5ki/ki x ApoE−/− mice by the injection of low-dose streptozotocin (STZ)." (PMID 35798762, 2022). "NOX5 in humans is a major source of ROS and contributes to both endothelial dysfunction and hypertension so may contribute to atherosclerosis." (PMID 36497101, 2022). "We first tested whether the knock-in of the Nox5 gene per se can induce atherosclerosis in aged mice exposed to a high cholesterol Paigen diet, which is atherogenic in other aged mouse models." (PMID 35798762, 2022). "Interestingly, Nox5 is not presented in the rodent genome that hinders the investigation of the role of Nox5 in atherosclerosis progression." (PMID 33510639, 2020). "Moreover, the magnitude of Nox5 expression and ROS generation correlated with the severity of atherosclerosis." (PMID 30334629, 2019). "Consequently, the precise implication of Nox5 in different pathologies and in particular in atherosclerosis remains elusive." (PMID 31565149, 2019). "However, the fact that NOX-5 is only expressed in humans has slowed down the progress in the elucidation of the impact of NOX-5 in atherosclerosis." (PMID 29099757, 2017).
atherosclerosis (continued). "The expression and activity of Nox5 are dramatically elevated in atherosclerosis, acute myocardial infarction, and fetal ventricular septal defect, which suggests that the dysregulation of Nox5 could contribute to cardiovascular disease in humans." (PMID 24505490, 2014). "The novel findings of our study, combined with results from previous studies showing KCNN4 plays a key role in regulating SMC phenotypic modulation and post-angioplasty restenosis, strongly support a role for NOX5 regulation of KCNN4 in the development of atherosclerosis and restenosis." (PMID 25144362, 2014). "However, the impact of NOX5 overexpression in atherosclerosis models remains less definitive." (PMID 40076813, 2025). "Finally, NOX-5 was found to be upregulated in atherosclerosis in the endothelium in the early lesions and in VSMC in the advanced coronary lesions and more recently, NOX-5 was found in human monocytes and macrophages and in macrophage-rich areas within human carotid artery atherosclerotic plaques." (PMID 29099757, 2017). "However, the role of NOX5 in human atherosclerosis remains unclear." (PMID 36497101, 2022). "Thus, we next decided to retest the Nox5 hypothesis of atherosclerosis under conditions where atherosclerosis is observed and determine whether Nox5 KI aggravates this phenotype in the atherosclerosis prone apolipoprotein E (ApoE−/−) mouse in both normal and diabetic conditions." (PMID 35798762, 2022). "Considering the critical role of Mac and Nox5-derived ROS in atherosclerosis, we designed experiments to search for the existence of mechanistic links between HAT system and Nox5 overexpression in Mac in atherosclerosis." (PMID 31565149, 2019). "Regardless, we demonstrated that a characteristic stimulus of numerous cardiovascular diseases, including arterial hypertension and atherosclerosis, could promote ECM remodeling through the NOX5/MMP-10 axis." (PMID 39456453, 2024). "The NOX5 gene is absent from rodent species and this has hampered our understanding of its role in atherosclerosis." (PMID 36497101, 2022). "In the heart, NOX5 plays a role in the regulation of intermediate‐conductance Ca2+‐activated K+ channels (KCNN4), important for coronary artery smooth muscle cell contraction and progression of atherosclerosis (Gole, Tharp, & Bowles, 2014)." (PMID 30801870, 2019). "Our findings provide novel evidence that NOX5-derived ROS increase functional expression of KCNN4 through activator protein-1, providing another potential link between NOX, CSMC phenotypic modulation, and atherosclerosis." (PMID 25144362, 2014). "Moreover, in the same work, the authors demonstrated that the endothelial expression of NOX5 did not aggravate aortic atherosclerosis in the atherosclerosis-prone ApoE−/− mice with and without induction of diabetes." (PMID 36905456, 2023). "A recent study using knock-in mice expressing human NOX5 in endothelial cells showed that NOX5 does not promote atherosclerosis, although deletion of NOX5 in New Zealand White rabbits significantly increased plaque development in the thoracic aorta, suggesting a protective role of NOX5." (PMID 36497101, 2022). "Based on the fact that oxidative stress is instrumental in atherogenesis, pharmacological targeting of epigenetic-based pathways that control Nox5 expression might be a noteworthy novel therapeutic strategy in atherosclerosis rather than direct scavenging ROS." (PMID 31565149, 2019). "However, not all models of vascular inflammation and remodelling are associated with NOX5, as demonstrated in a primate model of atherosclerosis, where NOX2, but not NOX5, was involved in vascular injury (Stanic, Pandey, Fulton, & Miller, 2012)." (PMID 30801870, 2019). "Given the central role of KCNN4 in phenotypic modulation and neointimal formation and the recently described role of NOX5 in human SMC proliferation and atherosclerosis, we tested the hypothesis that NOX5 is required for transcriptional upregulation of KCNN4 through AP-1." (PMID 25144362, 2014).
atherosclerosis (continued). "Thus Nox5-derived reactive oxygen species are not a new independent mechanism of atherosclerosis but may enhance the frequency of abdominal aortic aneurysms in the context of diabetes." (PMID 35798762, 2022). "However, whether just on a high cholesterol diet or by crossing in aortic atherosclerosis-prone ApoE−/− mice with and without induction of diabetes, Nox5 neither induced on its own nor aggravated aortic atherosclerosis." (PMID 35798762, 2022).